NOXRED1 (NADP dependent oxidoreductase domain containing 1)
Description:
Probable oxidoreductase.
Synonyms: C14orf148; FLJ32809
Tractability: Antibody: the Human Protein Atlas places it where antibodies can reach.
Gene: Protein-coding gene on chromosome 14 (77,394,021 to 77,423,523, reverse strand). Ensembl gene ENSG00000165555.
Subcellular location (Human Protein Atlas): Vesicles; Plasma membrane
Gene Ontology:
Molecular function: pyrroline-5-carboxylate reductase activity
Biological process: L-proline biosynthetic process
Genetic constraint (gnomAD): Loss-of-function variants: 17 observed, 26.78 expected, observed/expected ratio (o/e) 0.63, 90% interval 0.43 to 0.95. The upper end of that interval is the gene's LOEUF score, 0.95, which puts it in group 4 of 6, group 1 being the genes least tolerant of losing a copy. Missense variants: 315 observed, 370.7 expected, observed/expected ratio (o/e) 0.85, 90% interval 0.77 to 0.93. Synonymous variants: 132 observed, 146.26 expected, observed/expected ratio (o/e) 0.9, 90% interval 0.78 to 1.04.
Homologues: Orthologues: chimpanzee NOXRED1 (99% identical), macaque NOXRED1 (96% identical), dog NOXRED1 (74% identical), pig NOXRED1 (74% identical), mouse Noxred1 (61% identical), rat Noxred1 (58% identical), tropical clawed frog noxred1 (42% identical), zebrafish noxred1 (35% identical), Drosophila melanogaster P5cr (13% identical), Caenorhabditis elegans pycr-4 (10% identical). Paralogues in human: PYCR2 (16% identical), PYCR1 (16% identical), PYCR3 (12% identical).
Diseases named in the same sentence as NOXRED1 in open-access papers:
NOXRED1 is named in the same sentence as 1 disease in open-access papers, as found by Europe PMC text mining. Sharing a sentence is not in itself a finding about the gene and the disease.
NOXRED1 shares sentences with these, for which no sentence is quoted: cancer (1 paper).